TREM2 (triggering receptor expressed on myeloid cells 2)
Diseases named in the same sentence as TREM2 in open-access papers (continued):
Sharing a sentence is not in itself a finding about the gene and the disease.
Alzheimer disease (continued). "Ab-T1 was shown to bind its target TREM2 in the entorhinal cortex of human brains (cortex) and CSF from Alzheimer’s disease patients seen in Western blot." (PMID 37296669, 2023). "TREM2 target drugs are still early in their development, but their ability to alter TREM2 in early stages of Alzheimer’s disease has been found to promote cell survival and decrease amyloid levels in the brain." (PMID 37444065, 2023). "On the other hand, increased DNA methylation of CpG sites located upstream of the TREM2 transcription start site is reported in the superior temporal gyrus of patients with Alzheimer’s disease." (PMID 37107654, 2023). "TREM2 p.R47H carriers had reduced levels of microglial activation in brain regions affected early in the Alzheimer’s disease course and differences in brain structure and cognition." (PMID 37990275, 2023). "Previously, we reported that H157Y, a rare coding variant on exon 3 of the triggering receptor expressed on myeloid cells 2 gene (TREM2), was associated with Alzheimer’s disease (AD) risk in a Han Chinese population." (PMID 37190607, 2023). "In relation to Alzheimer’s disease, studies have found TREM2 expression leads to an increase in tau phosphorylation, but this relation has not been studied as much as TREM’s connection to amyloid-beta." (PMID 37444065, 2023). "Triggering receptor expressed on myeloid cells 2 (TREM2), a pathologically induced immune signaling in Alzheimer’s disease, metabolic diseases, and cancer, has been found to express in ATMs." (PMID 37153549, 2023). "Altered microglial activation, potentially via TREM2 modulation, is an exciting future target for novel therapeutics in Alzheimer’s disease that is currently undergoing preclinical trials." (PMID 37990275, 2023). "TREM2 is a transmembrane protein expressed by monocytic myeloid cells and is essential for the proper function of microglia in Alzheimer's disease and of macrophages in adipose tissue or liver under obese conditions." (PMID 37182562, 2023). "The signaling of TREM2 was found to increase amyloid-beta accumulation in early stages of Alzheimer’s disease and decrease amyloid-beta accumulation in later stages." (PMID 37444065, 2023). "Human longitudinal studies of Alzheimer’s disease patients show that a higher CSF soluble TREM2 levels predicts slower cognitive decline and attenuated amyloid and tau signal in positron-emission tomography." (PMID 37798310, 2023). "All three of the replicated genes have been previously associated with clinically diagnosed Alzheimer’s disease (SORL1, TREM2, and TOMM40/APOE)." (PMID 36750708, 2023). "A genome-wide association study (GWAS) has revealed over 40 genes associated with an increased risk of developing Alzheimer’s disease, including the highly expressed glia-specific genes APOE4, TREM2, ABCA7, and SORL1." (PMID 38031028, 2023). "Trem2 has been studied in Alzheimer’s disease, as its activation plays a role in the formation of pathologic β-amyloid, as well as that of lipoproteins and apolipoproteins." (PMID 36982629, 2023). "In a previous study of Alzheimer's disease, TREM2 was shown to help maintain the normal metabolism of microglia and it also took part in metabolic coordination between macrophages and hepatocytes." (PMID 37435171, 2023). "There have been contradictory findings regarding the potential detrimental or protective effects of microglial activation and TREM2-related microglial responses in Alzheimer’s disease." (PMID 37942087, 2023). "For example, DNA hypomethylation of TREM2 intron 1, which is associated with its increased expression, was shown in the blood cells of patients with SCZ and Alzheimer’s disease." (PMID 37107654, 2023). "The TREM2 p.R47H carrier and mild cognitive impairment groups had similar levels of Alzheimer’s disease pathology detected on PET." (PMID 37990275, 2023). "TREM2 governs the response of microglia to amyloid and tau pathologies in the Alzheimer’s disease (AD) brain." (PMID 36805764, 2023).
Alzheimer disease (continued). "The proteolytic shedding of TREM2 results in the release of soluble TREM2 (sTREM2), which is increased in the cerebrospinal fluid of patients with Alzheimer’s disease (AD)." (PMID 37865646, 2023). "Triggering receptor expressed on myeloid cells 2 (TREM2) has been postulated as a putative therapeutic target in Alzheimer’s disease (AD)." (PMID 37198381, 2023). "TREM2 has emerged as a pivotal target in therapeutic strategies for Alzheimer’s disease (AD) focused on modulating microglial activation and inflammatory responses." (PMID 38203185, 2023). "Microglia remove hyperactive phosphatidylserine‐positive synapses via TREM2 in Alzheimer's disease (AD) models supporting a beneficial role for microglia in AD." (PMID 37575021, 2023). "For example, the Alzheimer Disease (AD)-associated proteins APP, BACE1, Nicastrin, Tau, APOE and TREM2 all have several N- and O-glycosylations." (PMID 37201132, 2023). "In recent years, genome-wide association studies (GWAS) have identified more than 25 genetic loci that are strongly associated with the risk of developing late-onset Alzheimer’s disease (LOAD), one of them is TREM2 gene variants." (PMID 35663962, 2022). "In contrast, strategies employing agonistic compounds that enhance TREM2 signaling to boost the healing activities of macrophages and microglia are adopted for Alzheimer’s disease." (PMID 35359989, 2022). "With the realization of the importance of TREM2 in neuronal health, investigators have also shown that TREM2 plays a protective function against development of Alzheimer’s Disease." (PMID 36119485, 2022). "In an animal model of Alzheimer’s disease, CD45High cells had a higher phagocytic capacity and expressed TREM2 and CD11c, both of which are markers that resemble disease-associated microglia." (PMID 35850727, 2022). "Our result is consistent with the report that stimulation of the cGAMP-STING-IRF3 pathway induces the expression of TREM2 in Alzheimer's disease pathology." (PMID 35924849, 2022). "Up to this point, the majority of work on TREM2 has been conducted in the context of Nasu-Hakola Disease and Alzheimer’s Disease and the role of TREM2 in these settings has recently been reviewed elsewhere." (PMID 36119485, 2022). "TREM2 has been extensively studied in microglia for its capacity to sustain microglial responses to neurodegenerative pathologies, such as Alzheimer’s disease." (PMID 35359989, 2022). "Previous studies have reported TREM2 as a key player in Alzheimer’s disease and TYROBP as key gene for AS." (PMID 36552740, 2022). "To date, increasing evidence has shown the neuroprotective effects of TREM2 in Alzheimer’s disease, multiple sclerosis and Parkinson’s disease." (PMID 36463233, 2022). "Increased soluble TREM2 (sTREM2) in cerebrospinal fluid (CSF) is related to cognitive impairment in Alzheimer’s disease (AD) patients." (PMID 36585610, 2022). "Despite the central role of TREM-2 in Alzheimer’s disease, metabolic syndrome, cancer, and other diverse pathologies causing it to attract considerable recent attention, its role in RA is not well understood." (PMID 36012120, 2022). "TREM1 and TREM2 are better known for their contribution in Alzheimer disease, but in the last couple of years, many investigations have been conducted regarding their contribution to inflammatory processes after SAH." (PMID 36293468, 2022). "In a newly developed mouse model of genetic risk for sporadic or late-onset Alzheimer’s disease (LOAD mice) transgenic mice express humanized APOE4 and TREM2 alongside a humanized beta-amyloid precursor protein." (PMID 36532725, 2022). "TYROBP is the downstream adaptor and putative signaling partner for several receptors implicated in Alzheimer’s disease (AD), including SIRP1β, CD33, CR3, and TREM2." (PMID 36002854, 2022). "Soluble triggering receptor expressed on myeloid cells 2 (sTREM2) concentration is increased in cerebrospinal fluid (CSF) in early symptomatic phase of Alzheimer’s disease (AD)." (PMID 36585610, 2022).
Alzheimer disease (continued). "TREM2 plays a critical neuroprotective during early and mid-term Alzheimer's disease (AD), as it suppresses the Aβ diffusion and accumulation by regulating microglial activation around amyloid plaques." (PMID 35672339, 2022). "The analysis demonstrated that TREM2 activation was lower in Alzheimer's disease microglia than in microglia from healthy subjects." (PMID 34523252, 2021). "Microglial activation, as observed in Alzheimer’s disease (AD) as well as in transgenic mice expressing human amyloid-beta, appears to increase soluble TREM2 (sTREM2) levels in CSF and brain." (PMID 33620643, 2021). "Amyloid plaque formation is a primary diagnostic measure of Alzheimer’s disease with both APOE and TREM2 linked to amyloid deposition." (PMID 34707490, 2021). "Human CSF from Alzheimer’s disease patients was blotted with Ab-T1 to determine its ability to bind endogenous soluble human TREM2." (PMID 33422057, 2021). "Trem2 is a membrane receptor that binds a wide variety of ligands and is best known for its protective role in Alzheimer’s disease." (PMID 34776838, 2021). "Knockout of TREM2 in an Alzheimer’s disease (AD) mouse model inhibited microglial phagocytotic effects on removing Aβ plaques and cell debris as well as induced extracellular lipid accumulation and secondary inflammation." (PMID 34276309, 2021). "Human genetic studies have linked rare coding variants in microglial genes, such as TREM2, and more recently PLCG2 to Alzheimer’s disease (AD) pathology." (PMID 34615897, 2021). "Identification of TREM2 in this study is consistent with previous work and knowledge in AD, as TREM2 is one of the most widely studied genes in Alzheimer’s disease, with links to both amyloid and tau pathology." (PMID 33947463, 2021). "The removal of TGFβ leads to significant changes that have been identified as Alzheimer’s disease (AD) GWAS loci genes, including TREM2 and APOE, indicating the relevance of TGFβ for microglial homeostasis and maintenance." (PMID 33803024, 2021). "Ab-T1 was shown to bind its target TREM2 in a panel of entorhinal segments human brains (entorhinal cortex; ento cortex)) from Alzheimer’s disease patients and healthy subjects seen in Western blot." (PMID 33422057, 2021). "In mouse models of Alzheimer’s disease, enhancement of Trem2 signaling using agonistic antibodies has recently shown beneficial effects on cognitive function through attenuation of neuroinflammation and improved plaque clearance within the brain." (PMID 34851663, 2021). "Triggering receptor expressed on myeloid cells 2 (TREM2) is related to Alzheimer’s disease development." (PMID 34497631, 2021). "Whereas understudied in PDA, TREM2 has been extensively evaluated in Alzheimer’s disease, a neurodegenerative disease, which, like cancer, is marked by a chronic inflammatory response." (PMID 33782087, 2021). "Triggering Receptor Expressed in Myeloid Cells 2 (TREM2) is a pattern recognition receptor on myeloid cells, and is upregulated on microglia surrounding amyloid plaques in Alzheimer's disease (AD)." (PMID 35153729, 2021). "We report an effective surface immobilization protocol for capture of Triggering Receptor Expressed on Myeloid Cells 2 (TREM2), a receptor whose elevated concentration in cerebrospinal fluid has recently been associated with Alzheimer’s disease (AD)." (PMID 34356688, 2021). "TREM2 is a phospholipid sensing receptor known to sustain microglial cell activation and expansion in response to demyelination or amyloid plaques in Alzheimer’s disease (AD)." (PMID 32772264, 2020). "The Trem2 variant R47H, confers substantially elevated risk of developing late onset Alzheimer’s disease, while NHD-linked Trem2 variants like Y38C, are associated with development of early onset dementia with white matter pathology." (PMID 33115519, 2020).
Alzheimer disease (continued). "It is also shown to prevent the stimulation of TREM2 pathway, which is an important pathological factor in Alzheimer disease." (PMID 32864980, 2020). "In this study, we used single-nucleus RNA sequencing (snRNA-seq) of human tissue to characterize microglial responses to Alzheimer disease neuropathologic change as a function of APOE and TREM2 risk genotypes." (PMID 32840654, 2020). "Trem2−/− 5XFAD mice (an Alzheimer’s disease model) show impaired glycolysis, reduced ATP production, and increased autophagy in microglia." (PMID 32450896, 2020). "Phospholipids and lipoproteins (including Apoe which was reduced to some extent in response to SRT) have been identified as ligands for TREM2 in Alzheimer’s disease, which promotes microglia activation and survival." (PMID 32892753, 2020). "Recent studies revealed a critical role of TREM2/TYROBP signaling in the regulation of microglial phagocytosis in Alzheimer's disease and other neurological diseases." (PMID 33225612, 2020). "The triggering receptor expressed on myeloid cells 2 (TREM2)/apolipoprotein E (APOE) pathway has been in the focus of microglia analysis since it was shown that this pathway is important during Alzheimer’s disease progression as well as during EAE/MS." (PMID 33058309, 2020). "The expression of the TREM2 gene, whose product is thought to be protective in Alzheimer’s disease through promotion of amyloid clearance, was down-regulated in SIVE-Meth 3.3-fold, whereas TREM1 gene expression was increased 2.1-fold." (PMID 33198269, 2020). "The triggering receptor expressed on myeloid cells 2 (TREM2), a cell-surface receptor mainly expressed on microglia in the CNS, has been implicated in various diseases associated with Alzheimer’s disease, Nasu-Hakola disease, and neuropathic pain." (PMID 33081801, 2020). "Triggering receptor expressed on myeloid cells 2 (TREM2) is cleaved by ADAM10 at the H157-S158 bond, and the H157Y variant found in an Alzheimer disease patient increased its cleavage and caused a loss-of-function phenotype." (PMID 32873342, 2020). "Triggering receptor expressed on myeloid cells 2 (TREM2) has been shown with a neuroprotective function against inflammation and neuronal injury in Alzheimer’s disease (AD)." (PMID 33065553, 2020). "It has been reported that TREM2 binds to apolipoproteins including APOE, which is the strongest genetic risk factor for late-onset Alzheimer disease." (PMID 31649511, 2019). "It argues for a pan-organ role of Trem2 signaling in tissue macrophages that is beyond the limits of hepatology but that is definitively interesting considering what is known on the central role of Trem2 in Alzheimer disease for example." (PMID 31803196, 2019). "Rare coding variants in TREM2, PLCG2, and ABI3 were recently associated with the susceptibility to Alzheimer’s disease (AD) in Caucasians." (PMID 30705288, 2019). "Trem2 was shown to be expressed in the inflammatory macrophages and has a detrimental role in Alzheimer's disease pathology." (PMID 31849962, 2019). "Representative examples are triggering receptor expressed on myeloid cells-2 (Trem2), Cd33, Cr1, Mef2c, members of the MS4A family, and the HLA locus, which are Alzheimer’s disease (AD) risk genes." (PMID 31627485, 2019). "For example, we found Alzheimer’s Disease risk genes APOE, PLD3, TREM2, UNC5C, AKAP9, and ADAM10 in our orthologous gene list." (PMID 30382841, 2018). "The level of the soluble fragment of TREM2 (sTREM2) is reported to increase in the cerebrospinal fluid (CSF) already in prodromal and asymptomatic Alzheimer’s disease." (PMID 30390679, 2018). "Further research is needed to elucidate the biological role of TREM2 in the natural immune regulation of Alzheimer’s disease." (PMID 29655369, 2018). "Recent research has shown that the triggering receptor expressed on myeloid cells 2 (TREM2) in microglia is closely related to the pathogenesis of Alzheimer’s disease (AD)." (PMID 29655369, 2018).
Alzheimer disease (continued). "Modulating microglial activity through TREM2 has been proposed as a therapeutic target in Alzheimer’s disease." (PMID 28302159, 2017). "Triggering receptor expressed on myeloid cells 2 (TREM2) and apolipoprotein E (APOE) are genetically linked to Alzheimer’s disease." (PMID 28320424, 2017). "TREM2 is a receptor protein that allows microglia to sense and potentially engulf the amyloid plaques and cellular debris that characterise Alzheimer's disease." (PMID 28855301, 2017). "Soluble TREM2 cleaved from the surface of microglia has been proposed as a biomarker in other neurological diseases including Alzheimer’s disease and multiple sclerosis." (PMID 28302159, 2017). "In particular, a rare variant of triggering receptor expressed on myeloid cells 2 (TREM2), R47H, is associated with an increased risk for late onset Alzheimer’s disease (LOAD)." (PMID 28491064, 2017). "Gene network analysis by Zhang and colleagues identified a microglia specific module that includes TYROBP, the signaling adaptor protein of TREM2, as a key node of networks in late onset Alzheimer’s disease." (PMID 28923083, 2017). "Mutations and/or differential expression of microglial specific receptors such as TREM2, CD33, and CR3 have been associated with strong increased risk for developing Alzheimer’s disease (AD)." (PMID 28612290, 2017). "This is genetically supported by the association of microglia-specific genes, TREM2 and CD33, and late onset Alzheimer's disease." (PMID 29311768, 2017). "We first measured TREM2 mRNA levels in hippocampal samples from Alzheimer’s disease (AD) cases and controls by RT-qPCR." (PMID 27051467, 2016). "An important finding of this study is that TREM2 mRNA is significantly upregulated in the human hippocampus in Alzheimer’s disease (AD) and correlates with AD-related neuropathological changes." (PMID 27051467, 2016). "They further analyzed the differential gene expression of Trem2 over wide range of human brain areas in mice with Alzheimer’s disease and compared it with the control mice to study the genetic mutation and disease mechanism." (PMID 24663666, 2014). "Zhao and co-workers had recently described the regulation of TREM2 by a NF-kB-sensitive miRNA as a mechanism of TREM2 control in Alzheimeŕs disease patients." (PMID 23977213, 2013). "The human Triggering Receptor Expressed on Myeloid cells 2 (TREM2) gene is expressed predominantly by microglia in the brain and the R47H coding variant of TREM2 is associated with increased risk for late-onset Alzheimer's disease (LOAD)." (PMID 42102578, 2026). "Our application of Incytr to COVID-19 patient data, MC38, and 5XFAD mouse model data has recapitulated known biological system-specific signaling pathways such as cancer specific pathways, Alzheimer’s disease specific pathways such as Apoe-App, Apoe-Trem2, and Apoe-Lrp1." (PMID 39975141, 2025). "This differential expression of TREM2 across immune cell types underscores its pivotal role in orchestrating the immune response to a multitude of conditions, including various infectious diseases, Alzheimer's disease, and tumors." (PMID 40552184, 2025). "Finally, TREM2 is known to be involved in the amyloid pathology of Alzheimer’s disease through the regulation of glial cell proliferation, homing, and phagocytosis of amyloid plaques." (PMID 40940747, 2025). "TREM2 has been shown to play a vital role in cognitive-related neuroprotection in multiple diseases, such as nonalcoholic fatty liver disease, postoperative cognitive impairment, Nasu-Hakola disease, vascular dementia, and Alzheimer’s disease (AD)." (PMID 40393958, 2025). "Furthermore, mTORC1 activation in activated microglia has a significant role in phagocytosis, since rapamycin treatment decreases TREM2 expression in microglia and the clearance of β-Amyloid plaques in an Alzheimer’s disease mouse model." (PMID 40911604, 2025).